RN7SKP119 (RN7SK pseudogene 119)
Gene: Miscellaneous RNA gene on chromosome 2 (47,359,505 to 47,359,777, reverse strand). Ensembl gene ENSG00000222685.
Homologues: Orthologues: chimpanzee 7SK (98% identical), mouse Gm56256 (54% identical). Paralogues in human: 7SK (82% identical), RN7SKP176 (80% identical), RN7SKP80 (80% identical), RN7SKP37 (79% identical), RN7SKP79 (79% identical), RN7SKP71 (79% identical), RN7SKP173 (79% identical), RN7SKP246 (79% identical), RN7SKP255 (79% identical), RN7SKP9 (78% identical), RN7SKP203 (78% identical), RN7SKP47 (78% identical), and 283 more.